SNORD107 (small nucleolar RNA, C/D box 107)
Synonyms: HBII-436
Gene: Small nucleolar RNA gene on chromosome 15 (24,981,994 to 24,982,068, forward strand). Ensembl gene ENSG00000276314.
Gene Ontology:
Biological process: RNA processing
Cellular component: nucleolus
Homologues: Orthologues: macaque SNORD107 (100% identical), chimpanzee SNORD107 (99% identical), pig SNORD107 (88% identical), rat Snord107 (85% identical), mouse Snord107 (83% identical).
Diseases named in the same sentence as SNORD107 in open-access papers:
SNORD107 is named in the same sentence as 1 disease in open-access papers, as found by Europe PMC text mining. Sharing a sentence is not in itself a finding about the gene and the disease.
SNORD107 shares sentences with these, for which no sentence is quoted: leukemia (1 paper).